PXN (paxillin)
Diseases named in the same sentence as PXN in open-access papers (continued):
Sharing a sentence is not in itself a finding about the gene and the disease.
prostate carcinoma (26 papers, 2013 to 2026). A carcinoma that arises from epithelial cells of the prostate gland. "Study showed paxillin was associated with lymph node metastasis in prostate cancer, and downregulated paxillin suppressed the invasion of colon cancer cells." (PMID 34268882, 2021). "Abnormal paxillin expression is associated with many clinicopathological parameters such as aggressiveness, distant metastasis, and clinical stage in various tumors, including colorectal cancer, prostate cancer, salivary adenoid cystic carcinoma, and cervical cancer." (PMID 37175948, 2023). "Integrin-linked kinase (ILK), plectin (PLEC), paxillin (PXN), talin 1 (TLN1), and vinculin (VCL) are other adhesome proteins that were implicated in prostate cancer and that showed biomarker potential in this cancer type." (PMID 38255186, 2023). "For example, docetaxel inhibits the growth of prostate cancer cells and promotes apoptosis by inhibiting the phosphorylation level of paxillin." (PMID 37175948, 2023). "miR-125a-3p overexpression inhibits the activity of FYN, FAK, and paxillin, thus suppressing prostate cancer metastasis." (PMID 36740671, 2023). "Paxillin relates to cancer proliferation and metastasis, and PXN gene expression is relatively high in many cancers, including prostate cancer." (PMID 36289913, 2022). "A total of 85 genes were significantly highly expressed, and only PXN was downregulated in ETV4-fusion-positive prostate cancer." (PMID 36289913, 2022). "Leupaxin belongs to the group of paxillin proteins and was reported to play a major role in the invasion and migration of prostate cancer cells." (PMID 25955236, 2015). "PXN can act as a regulator in both castration‐sensitive prostate cancer and CRPC." (PMID 38842134, 2024). "For example, PXN, which is known as an oncogene in prostate cancer, has higher expression in the ERG and SPOP subtypes of prostate cancer, as compared to normal cells, and lower expression in ETV1 and ETV4 subtypes of prostate cancer, as compared to normal cells." (PMID 36289913, 2022). "Expression of paxillin, reported in prostate cancer and involved in cancer cell aggregation, could be implicated to this observation; further studies are needed to clarify this relationship." (PMID 34395260, 2021). "In prostate cancer, PXN acts as metastatic metastasis suppressor gene." (PMID 30200999, 2018). "The changes in localization of paxillin within the cell together with alterations in migration potential and prominent clustering at the cell periphery when HNF1B is over-expressed in prostate cancer models strongly suggest that loss of HNF1B expression has a fundamental role in EMT." (PMID 27732966, 2016). "Nuclear paxillin has also been observed to increase cell proliferation via transcription of Cyclin D1 in prostate cancer cells, by acting as a nuclear scaffold, to promote extracellular-regulated kinase (ERK) phosphorylation of the ETS domain-containing protein (Elk-1)." (PMID 26984511, 2016). "For example, up-regulation of PXN is found in non-small cell lung cancer and prostate cancer." (PMID 24180516, 2013). "However, more recent studies found PXN was overexpressed and acted as an pro-oncogene in a variety of tumors, including non-small cell lung cancer, colorectal cancer, prostate cancer and cervical carcinoma." (PMID 24180516, 2013). "Moreover, PXN expression in ETV4-fusion-positive prostate cancer was lower compared to normal." (PMID 36289913, 2022). "Maybe most interestingly in regard to our data on promotion of prostate cancer cell motility by PIM1 and NFATC1, there were several genes encoding regulators of the cytoskeletal actin network (INF2, FHOD1, ACTN3, CORO1B) and cell adhesion (COL6A2, PXN, ITGA5)." (PMID 31730483, 2019). "Paxillin has also been shown to increase the proliferation of HeLa, COS-7 and prostate cancer cells." (PMID 37667902, 2023).
prostate carcinoma (continued). "Growth differentiation factor 9 (GDF-9) has been reported to promote the metastatic ability of prostate cancer cells by promoting the expression of FAK and paxillin through a Smad-dependent pathway." (PMID 37175948, 2023). "Phosphorylation of PXN activated ERK/ELK1 and increased the transcription of c-FOS and cyclin D1, which in turn facilitated the proliferation of prostate cancer cells." (PMID 36923874, 2023). "PXN expression was relatively high in ERG1- and FLI1-fusion-positive prostate cancers and SPOP-mutant prostate cancer, but it was relatively low in ETV1- and ETV4-fusion-positive prostate cancers." (PMID 36289913, 2022). "In our study, we validate that endothelial cell induced autophagy reduced PXN and ZYX expression in AR positive prostate cancer cells." (PMID 30200999, 2018). "Western blot analysis shows that paxillin and zyxin are negatively related with LC3II, indicating the reported regulatory effect of autophagy on FAs also exists in prostate cancer cells." (PMID 30200999, 2018). "In prostate cancer cells, cytoplasmic cyclin D1/CDK4 complexes phosphorylate paxillin, a structural component of focal adhesions." (PMID 29066743, 2017). "The focal adhesion scaffold protein, PXN shuttles between focal adhesion sites and the nuclear matrix, interacts with AR and glucocorticoid receptor (GR) through the C-terminal LIM domain and functions as coactivator of both the receptors in prostate cancer." (PMID 40181329, 2025). "Despite PXN represents a valuable link between nuclear and extranuclear androgen action in prostate cancer cells, no similar evidence has been so far reported in skeletal muscle cells." (PMID 40181329, 2025). "Clinical samples from prostate cancer patients demonstrated that FYN, FAK and PXN expression levels were both increased with significant correlations, hence, FYN might be a prostate cancer molecular target." (PMID 36740671, 2023). "In addition, in migratory human prostate cancer cells, p21-activated kinase 4 (PAK4) was localized at focal adhesions, and was immunoprecipitated with paxillin and phosphorylated paxillin on Ser-27235." (PMID 31101859, 2019). "Considering that the androgen-receptor–paxillin complex occupies promoters of androgen-receptor-responsive genes, such as PSA (also known as KLK3) or NKX3-1 in prostate cancer cell line, it is worth exploring whether paxillin is employed here in a similar way." (PMID 26116569, 2015).
glioma (20 papers, 2008 to 2025). A benign or malignant brain and spinal cord tumor that arises from glial cells (astrocytes, oligodendrocytes, ependymal cells). "Likewise, they indicated that PXN plays as an oncogene in glioma progression and is associated with higher mortality in survival analysis." (PMID 38962075, 2024). "The decrease in the levels of integrin α6 and urokinase-type plasminogen activator receptor in glioma cells induced by penfluridol via focal adhesion kinase, paxillin, RAC, and Rho-associated coiled-coil containing kinases proteins activation was found reducing cancer cell migration and invasion." (PMID 36983018, 2023). "In contrast, p75NTR gene knockdown stimulates the expression of HIF-1α, fibronectin, and L1CAM, and the phosphorylation of Src, focal adhesion kinase (FAK), and paxillin, which increase the migration of C6 glioma cells." (PMID 35956937, 2022). "Next, we used the ZeroCostDL4Mic notebook to denoise data capturing the endogenous expression levels of a glioma cell endogenously labelled for paxillin-GFP, migrating on polyacrylamide hydrogel." (PMID 33859193, 2021). "FN is a marker for EMT-driven cancer stemness and induces EMT; increases the adhesion, proliferation and chemoresistance of glioma stem cells as well as their capacity for differentiation through the integrin/FAK/paxillin/AKT signaling pathway." (PMID 31334229, 2019). "Activation of focal adhesion kinase and phosphorylation of paxillin correlate with hypoxia-inducible migration of C6 glioma cells." (PMID 28798482, 2017). "Importantly, imatinib and nilotinib increased tyrosine phosphorylation of p130Cas, FAK, PXN and radial spheroid invasion in stem cell lines isolated from human glioma biopsies." (PMID 27293031, 2016). "However, we show here that both p130Cas expression and FAK kinase activity are required for the increased tyrosine phosphorylation of p130Cas, FAK, and PXN, and glioma cell spheroid invasion induced by imatinib and nilotinib." (PMID 27293031, 2016). "An important finding of this study is that, consistent with increased tyrosine phosphorylation of p130Cas, FAK, and PXN induced by imatinib and nilotinib treatment, these drugs strikingly increased motility in 2D and 3D models using multiple human glioma cell lines." (PMID 27293031, 2016). "However, PXN expression was upregulated in brain lower-grade glioma (LGG) (P < 0.01)." (PMID 34135128, 2021). "In glioma cells, CD155 mediates adhesion to the extracellular matrix protein vitronectin, promotes FA turnover and FA signaling towards SRC, paxillin, and p130CAS, and thereby contributes to tissue invasion." (PMID 35296518, 2022). "Apart from the B2M was abnormally upregulated, other recent reported molecules such as NUSAP1, Paxillin, CAVIN1, and PARP9 also overexpressed in glioma tissues." (PMID 33960680, 2021). "However, in RB-treated glioma cells, we found that Ca2+ was significantly elevated after activation of Na+-K+-ATPase by RB, which inhibited the Src/FAK/Paxillin focal adhesion pathway." (PMID 35656311, 2022). "Immunoprecipitation of p130Cas and subsequent immunoblotting showed that FAK and PXN were both constitutively complexed with p130Cas in U87MG glioma cells, and that these complexes were not affected by imatinib or nilotinib treatment." (PMID 27293031, 2016).
colon carcinoma (17 papers, 2002 to 2023). "Paxillin is one of the target genes of miR-137, and the overexpression of miR-137 can reduce the level of paxillin in colon cancer cells, which significantly inhibits cancer cell proliferation and metastasis." (PMID 37175948, 2023). "Inhibiting the expression of paxillin in M2 macrophages can inhibit their polarization by reducing the proliferation ability of colon cancer cells." (PMID 37175948, 2023). "In the nude mouse model, co-injection of colon cancer cells with wild-type or PXN-depleting macrophages significantly reduced the tumor size, suggesting that PXN can modulate the immune response and promote tumor growth." (PMID 36923874, 2023). "miR-218 and miR-27b can also regulate the occurrence and development of oral squamous cell carcinoma and colon cancer by targeting paxillin." (PMID 37175948, 2023). "Paxillin is phosphorylated at the tyrosine-88 residue (Y88-paxillin) by the oncogenic kinase Src to form pY88-paxillin, which is highly expressed in most human colon cancer tissues, and pY88-paxillin plays an oncogenic role in colorectal tumorigenesis." (PMID 37175948, 2023). "Previous work in colon cancer has shown that phosphatase and tensin homolog can inhibit PXN expression via PI3K/AKT/NF-kB signaling." (PMID 34135128, 2021). "The images obtained with a confocal microscope show a reduction in the fluorescence levels of the Vimentin and phospho-Paxillin proteins, confirming the beneficial role of GSEs on the inhibition of colon cancer progression." (PMID 32143529, 2020). "Consistent with our previous observation, knockout of PTPRT leads to increased levels of pY88 paxillin in colon tumors." (PMID 27447856, 2017). "A synthetic small molecule with anticancer effect inhibits FAK, Src, and paxillin expression and activation, leading to the suppression of cell migration in colon cancer cells." (PMID 29234409, 2017). "Consistently, phosphorylation of Y88 paxillin (pY88) is up-regulated in colon tumors derived from Apcmin+/− Ptprt−/− mice." (PMID 27447856, 2017). "We have shown previously that pY88 paxillin is up-regulated in a majority of human colon cancer specimens compared to matched normal colon tissues." (PMID 27447856, 2017). "Given that PTPRT dephosphorylates paxillin at Y88 residue, we performed immunohistochemistry staining of colon tumors harvested from the mice." (PMID 27447856, 2017). "Similar decreases in ERK1/2 and paxillin signaling upon KRS suppression were also observed in another colon cancer cell line, SW620, embedded in 3D collagen gels." (PMID 26091349, 2015). "Following on from this, we lastly examined the expressions of KRS, pERK1/2, and paxillin in clinical colon cancer tissues." (PMID 26091349, 2015). "In colon cancer, phosphorylation of PXN at tyrosines 31 and 118 site is essential for pressure-induced cellular metastasis and adhesion." (PMID 24180516, 2013). "A complex of Rgnef, FAK, and paxillin promote colon carcinoma tumor cell motility and matrix degradation in vitro with corresponding increases in tumor growth and surrounding tissue invasion in vivo." (PMID 22649559, 2012). "In addition, inhibiting the PI3k/Akt signaling pathway has also been shown to suppress the polarization of M2 macrophages by downregulating paxillin, thereby inhibiting the proliferation and invasion of colon cancer cells." (PMID 37175948, 2023). "Moreover, a reduction in protein expression levels of phospho-Rac1/Cdc42/Rac1/Cdc42 ratio, Cofilin, Vimentin, and phospho-Paxillin was found in both colon cancer cell lines studied." (PMID 32143529, 2020). "Moreover, compared to matched normal colon tissues, pY88 paxillin is up-regulated in a majority of human colon cancer specimens." (PMID 27447856, 2017). "Therefore, we suggest that an increased MMP2 expression by pBcl-2-S87 due to PXN-mediated ERK activation plays a crucial role in tumor invasion in colon cancer cells." (PMID 25826088, 2015).
colon carcinoma (continued). "PTEN can reduce the expression of paxillin by inhibiting the PI3K/AKT/NF-κB pathway, which plays a role in inhibiting the migration and invasion of colon cancer cells." (PMID 37175948, 2023). "The immunohistochemistry and western blot analysis in colon cancer cells overexpressing PTEN, exhibited decreased paxillin expression at both mRNA and protein levels, while the overexpression of paxillin reduced levels of PTEN and stimulated migration." (PMID 37853467, 2023). "We used the CPTAC dataset to investigate the differences in protein phosphorylation of PXN between tumor tissues and normal tissues across six types of tumors (BRCA, RCC, LUAD, ovarian cancer, colon cancer and UCEC)." (PMID 34135128, 2021). "A recent study has shown that PXN promotes cell proliferation and inhibits apoptosis in SW480 colon cancer cells." (PMID 25826088, 2015). "This was verified in other colon cancer cells showing decreases in ERK1/2 and paxillin expression and paxillin activity following YH16899 treatment." (PMID 26091349, 2015). "Phosphorylation of PXN at Y118 by FAK/Src pathway is essential for focal adhesion turnover and cell migration, and this PXN phosphorylation was frequently observed in colon cancer cells with aggressive phenotype." (PMID 25826088, 2015). "Similarly, treatment of Colo 320 colon carcinoma cells with the KKDC peptide enhanced cell spreading (KKDC) and focal complexes formation evident by paxillin staining (KKDC, inset)." (PMID 18545691, 2008).
colorectal cancer (17 papers, 2013 to 2025). A primary or metastatic malignant neoplasm that affects the colon or rectum. "Previous data confirmed that PXN expression was positively associated with the epithelial-mesenchymal transition process in different types of tumors, including colorectal cancer, RCC, and triple-negative breast cancer." (PMID 34135128, 2021). "To determine if varying levels of pY88 paxillin are associated with tumor prognosis, we stained a colorectal carcinoma tissue microarray with pY88 paxillin antibody for immunohistochemistry." (PMID 27447856, 2017). "We have previously found that PXN is up-regulated in colorectal cancer and associated with aggressive tumor phenotypes." (PMID 24180516, 2013). "Paxillin is known to acquire gain of function mutations that are associated with alterations in the malignant progression of many tumors including breast, lung, prostate, melanoma, and colorectal cancer." (PMID 28214467, 2017). "However, the underlying mechanism of PXN effects on tumor invasion and poor outcome in colorectal cancer patients is not fully understood." (PMID 25826088, 2015). "Similarly, paxillin expression is associated with survival and metastasis in colorectal cancer patients, and this may be a potential predictor of metastasis and an independent prognostic factor for recurrence but not for survival." (PMID 37175948, 2023). "In addition, Bcl-2 protein stability by PXN overexpression may partially contribute to PXN-mediated invasion and consequently to cause poorer survival in colorectal cancer patients who received 5-FU-based chemotherapy." (PMID 25826088, 2015). "In colorectal cancer cells, GA upregulated miR-1247-3p, leading to a reduction in integrin αV/β3 and inhibition of paxillin activation." (PMID 41226811, 2025). "On the other hand, inhibiting the activation of p-Erk in colorectal cancer cells by interfering with paxillin expression can increase the sensitivity of colorectal cancer cells to cetuximab." (PMID 37175948, 2023). "These pathways are related to neuroinflammation signaling, Fcγ receptor-mediated phagocytosis, paxillin signaling, colorectal cancer metastasis signaling, and signaling by Rho family GTPases." (PMID 37570327, 2023). "The interaction of paxillin with Bcl-2 has been reported to be responsible for 5-FU resistance in colorectal cancer." (PMID 37175948, 2023). "We also observed a positive correlation between PXN expression and survival prognoses in colorectal cancer, RCC, and BRCA." (PMID 34135128, 2021). "Knockdown of paxillin or ectopic expression of miR-137 inhibited tumor growth and metastasis of colorectal cancer (CRC) cells in vivo." (PMID 27999452, 2016). "Higher expression of paxillin and lower expression of miR-145 were observed in colorectal cancer tissues than corresponding paracancerous tissue." (PMID 27999452, 2016). "In conclusion, PXN promotes Bcl-2 phosphorylation at Serine 87 via PXN-mediated ERK activation, and its stabilization associated with increased tumor formation efficacy in mice and poor patient outcome in colorectal cancer patients." (PMID 25826088, 2015). "Immunostainings of 190 tumors resected from colorectal cancer patients indicated that PXN expression was positively correlated with Bcl-2, pBcl-2-S87, and MMP2 expression." (PMID 25826088, 2015). "Previously, it was identified that overexpression of wild-type paxillin plasmids promoted cell proliferation and also enhanced migration, invasive capacity and metastasis of the colorectal cancer cells." (PMID 24348846, 2014). "In addition, the downregulation of paxillin can inhibit the ERK signaling pathway to inhibit EMT in colorectal cancer cells by reducing the phosphorylation expression of ERK1/2 while keeping the total ERK1/2 level unchanged." (PMID 37175948, 2023). "Sphingosine kinase 1 may promote the invasive metastasis of colorectal cancer by driving autophagy to induce paxillin expression and its phosphorylation." (PMID 37175948, 2023).